NLRP9 (NLR family pyrin domain containing 9)
Description:
As the sensor component of the NLRP9 inflammasome, plays a crucial role in innate immunity and inflammation. In response to pathogens, including rotavirus, initiates the formation of the inflammasome polymeric complex, made of NLRP9, PYCARD and CASP1. Recruitment of proCASP1 to the inflammasome promotes its activation and CASP1-catalyzed IL1B and IL18 maturation and release in the extracellular milieu. The active cytokines stimulate inflammatory responses. Inflammasomes can also induce pyroptosis, an inflammatory form of programmed cell death. NLRP9 inflammasome activation may be initiated by DHX9 interaction with viral double-stranded RNA (dsRNA), preferentially to short dsRNA segments.
Synonyms: NALP9; NOD6; PAN12; CLR19.1
Tractability: No criterion of Open Targets' tractability assessment is met for any kind of drug.
Gene: Protein-coding gene on chromosome 19 (55,708,438 to 55,738,402, reverse strand). Ensembl gene ENSG00000185792.
Subcellular location: Cytoplasm; Inflammasome
Gene Ontology:
Molecular function: protein binding
Biological process: defense response to virus; innate immune response; positive regulation of interleukin-18 production; pyroptotic inflammatory response; regulation of inflammatory response
Cellular component: canonical inflammasome complex; cytoplasm
Genetic constraint (gnomAD): Loss-of-function variants: 83 observed, 80.31 expected, observed/expected ratio (o/e) 1.03, 90% interval 0.87 to 1.24. The upper end of that interval is the gene's LOEUF score, 1.24, which puts it in group 5 of 6, group 1 being the genes least tolerant of losing a copy. Missense variants: 1,277 observed, 1,202.1 expected, observed/expected ratio (o/e) 1.06, 90% interval 1.01 to 1.11. Synonymous variants: 508 observed, 455.29 expected, observed/expected ratio (o/e) 1.12, 90% interval 1.04 to 1.2.
Homologues: Orthologues: chimpanzee NLRP9 (99% identical), dog NLRP9 (68% identical), pig NLRP9 (62% identical), rat Nlrp9 (48% identical), mouse Nlrp9b (46% identical), mouse Nlrp9c (45% identical), mouse Nlrp9a (45% identical). Paralogues in human: NLRP4 (41% identical), NLRP12 (33% identical), NLRP3 (32% identical), NLRP14 (25% identical), NLRP1 (23% identical), NLRP13 (23% identical), NLRP2 (23% identical), NLRP5 (22% identical), NLRC5 (21% identical), NLRP11 (21% identical), NLRP7 (21% identical), NLRP8 (20% identical), and 8 more.
Diseases named in the same sentence as NLRP9 in open-access papers:
NLRP9 is named in the same sentence as 18 diseases in open-access papers, as found by Europe PMC text mining. Sharing a sentence is not in itself a finding about the gene and the disease. The quoted sentences say what the papers report.
glioma (2 papers, 2022 to 2023). A benign or malignant brain and spinal cord tumor that arises from glial cells (astrocytes, oligodendrocytes, ependymal cells). "Compared with normal tissues, except for MEFV, NLRP6, NLRP9, RIPK3, and ZBP1, the expression levels of the remaining genes were relatively high in glioma tissues." (PMID 37501725, 2023). "Three genes (NLRP2, NLRP9, and GSDMB) were downregulated, while the remaining 54 genes were upregulated in the glioma group." (PMID 35547808, 2022).
melanoma (2 papers, 2023 to 2024). A malignant, usually aggressive tumor composed of atypical, neoplastic melanocytes. "The fundamental constituent of inflammasomes, comprising pyrin, the NOD-like receptor (NLR) family (NLRP1, NLRP3, NLRP6, NLRP9, and NLRC4), and absent in melanoma 2 (AIM2)." (PMID 39125817, 2024).
multiple sclerosis (2 papers, 2020 to 2025). A progressive autoimmune disorder affecting the central nervous system resulting in demyelination. "Mutations in NLRP9 have already been found in patients with multiple sclerosis but also in patients with Alzheimer’s disease and colon cancer." (PMID 41062723, 2025). "Previous studies found that several variants in NLRP9 may influence the disease course in multiple sclerosis patients, as determined by an exome sequencing study, and may be associated with familial late-onset Alzheimer’s disease, as determined by a genome-wide association study." (PMID 32326631, 2020).
autoimmune disease (1 paper, 2018). A disorder resulting from loss of function or tissue destruction of an organ or multiple organs, arising from humoral or cellular immune responses of the individual to their own tissue constituents. "Despite that little evidence exists in the literature regarding its function, NLRP9 belongs to the NOD-like receptor (NLR) family of inflammasomes, which are known to play critical roles both in innate and adaptive immunity and whose dysfunction has strongly been linked to autoimmune diseases." (PMID 30217166, 2018).
Autoimmunity (1 paper, 2019). The occurrence of an immune reaction against the organism's own cells or tissues. "The activation of the inflammasome has been proposed as a mechanism of autoimmunity in MS patients, a hypothesis that is supported by rare variants in inflammasome components NLRP1, NLRP3, NLRP5 and NLRP9 which were identified in MS families, or found to correlate with disease course and severity." (PMID 31170158, 2019).
colonic cancers (1 paper, 2021). "In this study, we analyzed mononucleotide repeats in coding sequences of NLRP1, NLRP2, NLRP4 and NLRP9, and found 1, 1, 1 and 8 frameshift mutation (s) in gastric (GC) and colonic cancers (CRC), respectively." (PMID 34257569, 2021).
maturity-onset diabetes (1 paper, 2022). "NLRP9 was related to drug metabolism by cytochrome, maturity-onset diabetes of the young, metabolism of xenobiotics by cytochrome, ribosome, spliceosome, and valine, leucine, and isoleucine degradation." (PMID 36685920, 2022).
viral infections (1 paper, 2026). "This comprehensive review synthesizes the diversified landscape of inflammasome activation during viral infections, extending beyond the canonical NLRP3 inflammasome to include specialized sensors such as NLRP6, NLRP9, NLRP1, NLRP12, and NLRC4." (PMID 42198749, 2026).
xerostomia (1 paper, 2022). Dryness of the mouth resulting from reduced salivary secretion. "Our study also reported that NLRP9 was potentially associated with increased risk of reporting moderate to severe xerostomia." (PMID 35459784, 2022). "The most prominent findings in our study included potential associations of ANTXR1, RTP1, GLT1D1, NLRP9, and EGFLAM genes with xerostomia." (PMID 35459784, 2022). "It is important to note that inflammation is postulated to contribute to acute xerostomia during and immediately after HNC treatment, and our findings of a potential association between NLRP9 and xerostomia may provide some evidence to support this hypothesis." (PMID 35459784, 2022).
cancer (3 papers, 2021 to 2022). A tumor composed of atypical neoplastic, often pleomorphic cells that invade other tissues. "Together, these data suggest that NLRP9 expression is common in both normal and cancer cells of stomach and colon, and that frameshift mutations and expression loss of NLRP9 is frequent in GC and CRC with MSI-H." (PMID 34257569, 2021). "The mutations were frequent in both MSI-H GC (15.5%) and CRC (5.5%); NLRP9 mutations revealed ITH; and NLRP9 expression was frequently lost in NLRP9-mutated cancers." (PMID 34257569, 2021). "NLRP9 expression was negative in all cancers with its frameshift mutations." (PMID 34257569, 2021). "A majorly pan-cancer positive correlation between promotor methylation and gene expression of GSDMA, CASP1, NLRP9, GZMB, DHX9, DDX3X, SFRS2IP (CASP11) and GPX4 was observed." (PMID 36605187, 2022). "CTSG, NLRP9, DFNB59, APIP, SCAF11, CASP5 and NAIP showed significant downregulation across cancers." (PMID 36605187, 2022). "In cancers, the MSS (71.1%, 64/90) and MSI-H (64.8%, 94/145) cancers exhibited no statistically different prevalence in NLRP9 expression (Fisher’s exact test, p = 0.197)." (PMID 34257569, 2021). "Neither cancer-related functions nor gastrointestinal functions of NLRP9 gene have been identified." (PMID 34257569, 2021).
tumor (3 papers, 2021 to 2022). "Based on the hazard ratio (HR), the downregulated PLCG1, CASP6, CASP4, and AIM2 were considered tumor suppressors, whereas the upregulated PRKACA, NLRP9, and BAK1 were regarded as oncogenes." (PMID 34805183, 2021).
infection (1 paper, 2016). The state of being infected such as from the introduction of a foreign agent such as serum, vaccine, antigenic substance or organism. "The expression of PRRs involved in sensing nucleic acids (TLR3 and IFI16) and the NOD-like receptor NLRP9 increased following infection." (PMID 27677841, 2016).
NLRP9 also shares sentences with these, for which no sentence is quoted: breast carcinoma (1 paper); colorectal cancer (1); gout (1); late-onset Alzheimers disease (1); liver cancer (1); thyroid cancer (1).